SPINK5 (serine peptidase inhibitor Kazal type 5)
Diseases named in the same sentence as SPINK5 in open-access papers (continued):
Sharing a sentence is not in itself a finding about the gene and the disease.
Netherton syndrome (continued). "Netherton syndrome (NS) is a rare, autosomal recessive genodermatosis resulting from mutations in the SPINK5 gene, which encodes the LEKTI (Lympho-Epithelial Kazal-type-related inhibitor) protein." (PMID 40899446, 2025). "Matriptase was also implicated in Netherton Syndrome (NS), an epidermal disorder caused by mutations in the SPINK5 gene, which encodes for the Lympho-Epithelial Kazal-Type-related Inhibitor (LEKTI)." (PMID 34503205, 2021). "The importance of epithelial protease inhibitors has been revealed impressively in Netherton Syndrome (NS; OMIM 256500), an autosomal recessive disorder caused by mutations in the serine protease inhibitor Kazal-type 5 (Spink5) gene." (PMID 19190773, 2009). "Netherton syndrome (NS) is a rare congenital ichthyosis caused by loss-of-function mutations in the SPINK5 gene, leading to defective expression of the serine protease inhibitor LEKTI." (PMID 40888388, 2025). "In Spink5−/−Klk5−/−, Klk5 was genetically ablated on the Netherton background to provide proof of concept for drugging the KLK5 activity for pharmacotherapy of Netherton syndrome and, potentially, other diseases like atopic dermatitis." (PMID 35652924, 2022). "SPINK5 knockout mice (Spink5−/−) have been used to investigate the lack of one key serine protease inhibitor LEKTI, which models the human disease Netherton syndrome." (PMID 32903402, 2020). "Krystal Biotech is investigating the potential of topically administering the SPINK5 gene via non-integrating herpes simplex virus type 1 (HSV1) vectors to treat Netherton’s syndrome." (PMID 34684016, 2021).
asthma (19 papers, 2009 to 2025). "SPINK5 polymorphisms/haplotypes have also been associated with asthma susceptibility in numerous populations." (PMID 28552993, 2017). "In order to determine the role of the SPINK5 promoter polymorphism in the pathogenesis of asthma, we genotyped a promoter polymorphism, -206G>A, in 422 asthma patients and 410 controls, and found a marginal association." (PMID 19534795, 2009). "Our findings indicate that the -206G>A polymorphism in the SPINK5 is associated with asthma susceptibility in a Chinese Han population." (PMID 19534795, 2009). "Recently, single nucleotide polymorphism (SNP) of the SPINK5 was shown to be significantly associated with atopy, atopic dermatitis, asthma, and total serum IgE." (PMID 19534795, 2009). "SPINK5 is expressed in the skin and tonsil and has been linked with atopic dermatitis and asthma." (PMID 34202399, 2021). "One of 4 genes that was induced in controls at T2 compared to baseline was SPINK5, which has been intensely studied in asthma due to its location within chromosome 5q31-33, a region shown in genome-wide linkage scans to be linked to asthma and atopy." (PMID 28552993, 2017). "An epidemiological research with case–control design in Chinese Han population indicated that −206 G > A mutation produced GATA3 binding site in SPINK5 promoter and that the G allele was significantly more common among patients with asthma than among the controls." (PMID 24894987, 2014). "Furthermore, mutations in the serine peptidase inhibitor SPINK5 have been associated with asthma and SPINK5 was suggested to play a role in mucin production." (PMID 24282527, 2013). "In summary, although previous studies indicated that coding SNPs in the SPINK5 might be associated with asthma, we were unable to detect an association between the polymorphisms in the coding region of the SPINK5 and asthma risk in the Chinese Han population." (PMID 19534795, 2009). "However, we detected a significant association between -206G>A polymorphism in SPINK5 promoter and asthma." (PMID 19534795, 2009). "Also, epithelial eQTL supported SPINK5 as an asthma susceptibility gene." (PMID 27658857, 2016). "The differentially expressed genes included those related to inflammation (CCL22, CXCL16, AREG, MMP12) involved in asthma pathophysiology, as well as genes associated with the skin barrier (IVL, CDSN, SPINK5, FLG)." (PMID 39451560, 2024). "The SPINK5 encodes the lymphoepithelial Kazal-type-related inhibitor (LEKTI), a 15-domain serine protease inhibitor, and is located on chromosome 5q31-32, a region repeatedly found to be linked to asthma." (PMID 19534795, 2009). "In order to determine the role of the SPINK5 in the development of asthma, a case-control study including 669 asthma patients and 711 healthy controls in Han Chinese was conducted." (PMID 19534795, 2009). "In a translational aspect, the known dysregulation of Spink5 and Scca1 in children with asthma could therefore indicate to subtle deficits in the airway structure." (PMID 39019933, 2024). "Studies have shown that SPINK5 has biological actions other than protease inhibition, which may be related to the pathogenesis of asthma." (PMID 35600600, 2022). "Inoculation with HRV-16 upregulated Spink5 in nasal samples from healthy individuals which was not seen in asthma patients." (PMID 39019933, 2024). "Asthma is believed to have a strong genetic background, and hundreds of genes have been identified to be related with asthma, including GSTM1, IL10, CTLA-4, SPINK5, LTC4S, IL4R, and ADAM33." (PMID 24790987, 2014). "However, because our patients were ascertained for asthma, we could not exclude a role of the coding SNPs of the SPINK5 in atopic dermatitis in our population." (PMID 19534795, 2009).
ichthyosis (18 papers, 2010 to 2025). Disorders of cornification that are characterized by visible scaling and/or hyperkeratosis of most or all of the skin. "Taken together, the present study of four Pakistani families supports previous research that biallelic mutations in TGM1, SULT2B1, SPINK5, and FLG cause human ichthyoses." (PMID 33807935, 2021). "However, skin of newborn Spink5−/− mice grafted onto nude mice and analyzed 5 weeks later retained an ichthyosis-like phenotype." (PMID 33652877, 2021).
atopic dermatitis (16 papers, 2007 to 2025). "In a meta-analysis published in 2020, the SPINK5 Asn368Ser polymorphism was identified as a potential risk factor for atopic dermatitis alone." (PMID 39859044, 2025). "Previously, increased epidermal levels of unsaturated fatty acids as found in atopic dermatitis and SPINK5-sEDD were associated with defects in epidermal barrier due to reduction in packing density." (PMID 40943523, 2025). "Herein, we report an NS patient, initially misdiagnosed with severe atopic dermatitis, who carried a heterozygous frameshift (null) mutation combined with a homozygous single-nucleotide polymorphism of the SPINK5 gene." (PMID 37239440, 2023). "The SPINK5 (NM_006846.4): c.1258A>G polymorphism (rs2303067) shows a significant association with atopy and atopic dermatitis (AD), which share several clinical features with NS." (PMID 37239440, 2023). "Variants in SPINK5 are linked to Netherton syndrome, a rare genetic disorder characterized by severe skin disease, hair abnormalities, and atopic manifestations, including atopic dermatitis." (PMID 39859044, 2025). "Furthermore, mutations in SPINK5 have also been associated with atopic dermatitis, further highlighting the relevance of the Spint1a-deficient zebrafish model." (PMID 34748530, 2021). "Lastly, we extended the comparison of the Spink5 cKO skin differential gene expression profile to that of other inflammatory skin diseases, namely psoriasis (PsO) and atopic dermatitis (AD) patients." (PMID 38316920, 2024). "This study aimed to investigate the role of serine protease inhibitor Kazal-type 5 (SPINK5) polymorphisms (Asn368Ser, Asp386Asn and Glu420Lys) and the risk of atopic dermatitis (AD)." (PMID 32664181, 2020). "Finally, a bispecific KLK5/KLK7 antibody has been generated and tested in the mouse model of SPINK5-sEDD and atopic dermatitis." (PMID 40943523, 2025). "Consistent with this hypothesis, the exC3 cluster contained two genes (SPINK5 and FLG) previously recognised to confer susceptibility to childhood atopic dermatitis (AD), and one (CDSN) which has been implicated in psoriasis." (PMID 19888454, 2009). "However, the improvement effect of atopic dermatitis through the skin barrier function related to SPINK5 has not been studied." (PMID 35955819, 2022).
esophageal cancer (10 papers, 2014 to 2025). A primary or metastatic malignant neoplasm involving the esophagus. "SPINK5, whose expression is reduced at both mRNA and protein levels in esophageal cancer and associated with tumor progression, has been suggested as a potential biomarker, although its role in colitis and CRC remains unclear." (PMID 40977735, 2025). "According to research, SPINK5 is considerably downregulated in oesophageal cancer, head and neck SCC (HNSCC), and bladder transitional cell carcinoma." (PMID 40872585, 2025). "SPINK5 suppresses glycogen synthase kinase-3β (GSK3β) phosphorylation in oesophageal cancer, resulting in β-catenin breakdown and reduced tumor cell proliferation, relocation, and invasion." (PMID 40872585, 2025). "The Wnt/β-catenin signaling pathway can be inhibited by SPINK5 in order to act against esophageal cancer cells proliferation, migration, and invasion." (PMID 39867879, 2024). "Compared with that in normal esophageal tissue, the expression level of SPINK5 mRNA and protein in esophageal cancer tissue (including squamous cell carcinoma tissue) is significantly lower and predicts tumor lymph node metastasis and differentiation." (PMID 35223512, 2022). "Similar to the case in esophageal cancer, SPINK5 is downregulated in 85.7% of head and neck squamous cell cancer (HNSCC) cases and is an independent prognostic predictor for HNSCC patients." (PMID 35223512, 2022). "SPINK5 can inhibit GSK3β phosphorylation and promote β-catenin protein degradation, thereby inhibiting the proliferation, migration and invasion of esophageal cancer cells." (PMID 35223512, 2022). "SPINK5 had been shown to inhibit the proliferation, migration, invasion, and migration of esophageal cancer cells via the Wnt/β-catenin signaling pathway." (PMID 34336110, 2021). "The expression of SPINK5 in esophageal cancer cells was significantly reduced, and its anticancer effect was very significant." (PMID 34336110, 2021). "In vivo study, SPINK5 overexpression can significantly inhibit the growth of esophageal cancer cells." (PMID 30868765, 2019). "We used LiCl to activate the Wnt/β‐catenin signaling pathway, and then observed the effect of overexpression of SPINK5 on the proliferation and migration of esophageal cancer cells by plate colony formation assay and Transwell assay." (PMID 30868765, 2019). "We examined the effect of SPINK5 on the migration and invasion of esophageal cancer cells by Transwell assay." (PMID 30868765, 2019). "When the expression level of SPINK5 protein was lower, the pathological differentiation of esophageal cancer patients was lower, and lymph node metastasis was more likely to occur." (PMID 30868765, 2019). "In this study, we first explored the mechanism of action of SPINK5 in the development of esophageal cancer." (PMID 30868765, 2019). "In this study, we found through bioinformatics analysis that the expression level of SPINK5 is closely related to Wnt/β‐catenin signaling pathway in esophageal cancer." (PMID 30868765, 2019). "The results showed that the expression of SPINK5 protein was significantly reduced in 11 cases (11/12) of esophageal cancer, compared with normal esophageal tissues." (PMID 30868765, 2019). "We constructed a SPINK5 overexpressing ECA109 esophageal cancer cell line, which was then implanted subcutaneously in nude mice." (PMID 30868765, 2019). "We first constructed the overexpression plasmid and siRNA of SPINK5 and then transfected into esophageal cancer cells KYSE510 and ECA109." (PMID 30868765, 2019). "We have found that the expression level of SPINK5 is significantly reduced during the development of esophageal cancer, so what role does SPINK5 play in the development of esophageal cancer?" (PMID 30868765, 2019).
esophageal cancer (continued). "Then, CCK‐8 assay and plate cloning assay were used to detect the effect of SPINK5 on the proliferation of esophageal cancer cells." (PMID 30868765, 2019). "The results of the In vitro study further demonstrated that SPINK5 significantly inhibits the activity of the Wnt/β‐catenin signaling pathway in esophageal cancer cells." (PMID 30868765, 2019). "There are no studies to determine the difference in the expression levels of SPINK5 in normal esophageal and esophageal cancer tissues." (PMID 30868765, 2019). "In esophageal cancer cells, we have determined that SPINK5 regulates the Wnt/β‐catenin signaling pathway." (PMID 30868765, 2019). "We analyzed the GEPIA database and found that the expression level of SPINK5 mRNA in esophageal cancer tissues was significantly lower than that in normal esophageal tissues." (PMID 30868765, 2019). "To further validate the association of SPINK5 with Wnt/β‐catenin signaling pathways in esophageal cancer, we used bioinformatics to analyze the correlation between the expression levels of SPINK5 and Wnt/β‐catenin signaling pathways." (PMID 30868765, 2019). "Overexpression of SPINK5 could significantly inhibit the proliferation, migration, and invasion of esophageal cancer cells." (PMID 34336110, 2021). "In addition, we further verified the effect of SPINK5 on the growth of esophageal cancer cells in nude mice." (PMID 30868765, 2019). "In esophageal cancer cells, SPINK5 overexpression can inhibit Wnt/β‐catenin signaling pathway." (PMID 30868765, 2019). "In addition, in this study, we also found that SPINK5 is mainly expressed on the cell membrane in normal esophageal tissues, while SPINK5 is mainly in the cytoplasm and nucleus in esophageal cancer tissues." (PMID 30868765, 2019). "Therefore, we detected the expression level of SPINK5 protein in 12 cases of esophageal cancer tissues and their matched normal esophageal tissues by immunohistochemistry." (PMID 30868765, 2019). "Deletion of chromosome arm 5q, which contains Spink5, has been reported in human esophageal cancer." (PMID 25474466, 2014). "On the other hand, SPINK5 acted as a tumor suppressor in esophageal cancer, and which could inhibit the proliferation, migration, and invasion of esophageal cancer cells by inhibiting the Wnt/β-catenin signaling pathway and may serve as a therapeutic target for esophageal cancer." (PMID 37990105, 2023). "In addition, the inhibitory effect of SPINK5 overexpression on the growth of esophageal cancer cells was further verified in nude mice, suggesting that SPINK5 may be a new therapeutic target for esophageal cancer." (PMID 30868765, 2019). "Our study shows that SPINK5 can inhibit the proliferation, migration, and invasion of esophageal cancer cells by inhibiting Wnt/β‐catenin signaling pathway, and thus plays an important role in the development of esophageal cancer, and may serve as a treatment target of esophageal cancer." (PMID 30868765, 2019). "Furthermore, we verified whether SPINK5 affects the proliferation and migration of esophageal cancer cells via the Wnt/β‐catenin signaling pathway." (PMID 30868765, 2019). "In this study, we found that a novel tumor suppressor SPINK5 is significantly reduced in the development of esophageal cancer, and is closely related to the pathological differentiation and lymph node metastasis of esophageal cancer via bioinformatics analysis and esophageal cancer tissue array." (PMID 30868765, 2019). "The results showed that overexpression of SPINK5 significantly inhibited the proliferation of esophageal cancer cells KYSE510 and ECA109, while knockdown of SPINK5 significantly promoted proliferation of esophageal cancer cells KYSE510 and ECA109." (PMID 30868765, 2019). "Transwell migration assay showed that overexpression of SPINK5 significantly inhibited the migration of esophageal cancer cells KYSE510 and ECA109, while knockdown of SPINK5 significantly promoted the migration of esophageal cancer cells KYSE510 and ECA109." (PMID 30868765, 2019).
esophageal cancer (continued). "The results showed a significant correlation between the expression levels of SPINK5 and β‐catenin (CTNNB1), LRP5, LRP6, DVL3, LEF1, AXIN2, MYC, and cyclin D1 (CCND1) in esophageal cancer." (PMID 30868765, 2019). "In esophageal cancer cells KYSE510 and ECA109, we transfected SPINK5 overexpression plasmid and siRNA, respectively, and then detected the expression levels of key factors of Wnt/β‐catenin signaling pathway by western blot." (PMID 30868765, 2019). "In esophageal cancer cells, we overexpressed β‐catenin (GFP‐β‐catenin) in combination with protease inhibitor MG132, the results showed that MG132 significantly upregulated the expression of GFP‐β‐catenin and reversed the overexpression of SPINK5 to inhibit GFP‐β‐catenin." (PMID 30868765, 2019).
allergic disease (7 papers, 2009 to 2024). An immune response that occurs following re-exposure to an innocuous antigen, and that requires the presence of existing antibodies against that antigen. "Surprisingly, we found unchanged levels of the allergy-associated cytokine TSLP in skin of Spink5 cKO mice, which contradicts previous studies with Spink5-/- mice, showing TSLP up-regulation in keratinocytes through KLK5-mediated PAR-2 activation." (PMID 38316920, 2024). "The expression of Ccl8, known to attract actors of allergy and inflammation, was elevated in both Spink5-/- and Spink5-/-Klk5-/- skin, whereas Ccl20, a chemoattractant for CCR6+ cells including dendritic cells and Th17 cells, showed a significant increase only in Spink5-/- skin." (PMID 26390218, 2015). "Quantitative RT-PCR analyses and immunostainings revealed absence of inflammation and allergy in Spink5-/-Klk5-/- skin." (PMID 26390218, 2015).
eczema (5 papers, 2009 to 2023). "Variants mapped in both kallikrein-encoding genes (e.g., KLK7), as well as serine protease inhibitors (e.g., SPINK5), have been associated with eczema." (PMID 37373692, 2023). "Additional eczema risk genes were previously reported for monogenic diseases, including SPINK5 underlying autosomal-dominant Netherton syndrome, CARD11 for autosomal-dominant immunodeficiency 11B, and STAT3 for autosomal-dominant hyper-IgE recurrent infection syndrome." (PMID 38835414, 2023). "With their slow but consistent development of pruritus and eczema, PAR2OE mice mimic the clinical course of AD in children closer than other mouse models of AD (e.g., flaky tail mouse, SPINK5−/−, or filaggrin−/−)." (PMID 32903402, 2020).
Hyperkeratosis (5 papers, 2009 to 2024). Hyperkeratosis is a histopathological term defining a thickened stratum corneum and may be present in many different skin conditions, with many possible overlaps. "Histological analyses of skin samples from Spink5 cKO mice revealed stratum corneum detachment with parakeratosis and hyperkeratosis." (PMID 38316920, 2024). "Histological examination of Spink5-/- skin revealed epidermal hyperplasia, hyperkeratosis and parakeratosis, typical features of NS skin, consistent with compensatory hyperproliferative mechanisms secondary to skin barrier defects." (PMID 26390218, 2015). "Defective skin barrier as observed in NS patients and in Spink5-/- mice results in the development of compensatory mechanisms in the epidermis leading to hyperkeratosis (thickening of the cornified layer) and acanthosis (thickening of the living layers)." (PMID 26390218, 2015). "Hyperkeratosis in epidermis is thoroughly regulated by serine proteases such as KLK5 or KLK7 and serine protease inhibitors such as SPINK5." (PMID 33652999, 2021). "In contrast, histology examination of skin sections from Spink5-/-Klk5-/- mice showed neither acanthosis nor hyperkeratosis, nor microscopic separation of the stratum corneum/stratum granulosum." (PMID 26390218, 2015).